MDM2 (MDM2 proto-oncogene)
Diseases named in the same sentence as MDM2 in open-access papers (continued):
Sharing a sentence is not in itself a finding about the gene and the disease.
osteosarcoma (continued). "Mdm2 leads to the degradation of RARα, thereby impairs ATRA-induced osteogenic differentiation in osteosarcoma cells." (PMID 34769401, 2021). "To summarize, hsa_circ_0000073 enhances osteosarcoma cells’ malignant behavior by sponging miR-1252-5p and modulating CCNE2 and MDM2." (PMID 34568326, 2021). "MDM2 and CDK4 immunohistochemistry has been shown to be a valuable tool in differentiating low-grade osteosarcomas from other primary fibro-osseous lesions of long bones." (PMID 35049602, 2021). "Our results are consistent with experiments in osteosarcoma cell lines that have shown that drug treatment induces growth arrest and increases levels of CDKN1A, MDM2, and BCL2L1." (PMID 24835790, 2014). "Similar phenomena were observed in human osteosarcoma SJSA-1 cells, which harbor MDM2 amplification." (PMID 23638184, 2013). "Although not yet tested in dedicated osteosarcoma cohorts, their safety and efficacy in MDM2-amplified solid tumors provide a critical foundation for the development of precision medicine and combination regimens for osteosarcoma." (PMID 41901322, 2026). "A major obstacle hindering a more comprehensive global gene expression analysis is the rarity of MDM2-amplified osteosarcomas and the general lack of publicly available RNA data from osteosarcoma." (PMID 39322633, 2024). "For example, USP7 is known to be upregulated in osteosarcoma, but its ability to increase MDM2 levels in that context has not been investigated." (PMID 38534381, 2024). "Osteosarcoma is not an exception: MDM2 levels are increased in the low-grade, low-differentiated forms of the malignancy, and have been proposed to be used as a marker to identify the more aggressive subgroups." (PMID 38534381, 2024). "We inhibited the MDM2 proto-oncogene using this system in vitro, which efficiently inhibited the malignant behavior of osteosarcoma cells and induced apoptosis without affecting normal cells." (PMID 37415116, 2023). "Usually, DDLPS with osteosarcomatous change will co-exist with a WDLPS component, and show amplification of CDK4 in addition to MDM2, features not seen in primary osteosarcoma." (PMID 37504306, 2023).
osteosarcoma (continued). "Amplification of MDM2 which can be detected by fluorescence in-situ hybridization (FISH) is highly specific for osteosarcoma and absent in benign fibro-osseous lesions." (PMID 35875137, 2022). "Interestingly, MCC cell lines have much lower steady-state levels of MDM2 as compared with those of the osteosarcoma cell line SJSA-1 and the choriocarcinoma cell line JAR with MDM2 amplification, but they have a similar range of milademetan IC50 values." (PMID 35801592, 2022). "The presence or absence of MDM2 amplification in the group of low-grade osteosarcomas was not sufficient alone to explain the fragmentation of this tumor class." (PMID 35347251, 2022). "Osteosarcoma-derived CTCs were assayed for MDM-2 and KRAS amplification, highlighting a difference between patients diagnosed with metastasis in the lung or localized osteosarcoma, thus predicting the onset of metastatic lesions at distant sites and potentially the therapeutic efficacy of drugs." (PMID 34063272, 2021). "In addition, the finding of MDM2 and/or CDK4 amplification/overexpression in a high-grade osteosarcoma indicates progression/dedifferentiation from a low-grade osteosarcoma and practically excludes a primary conventional high-grade osteosarcoma." (PMID 33799733, 2021). "Furthermore, two out of these three (cases 1 and 4) showed nuclear immunoreactivity to MDM2 and CDK4, indicating their compatibility with low‐grade osteosarcoma." (PMID 34008925, 2021). "In the osteosarcoma U-2 OS cells, BBR and BBR nanoparticles made of heparin (HP), reduced cell viability, arrested the cell cycle in the G1 phase, and reduced expression of the mouse 2 min 2 homologs (MDM2)." (PMID 34885950, 2021). "Case 2 also seemed to morphologically has low‐grade osteosarcoma features, although MDM2 and CDK4 were not expressed immunohistochemically." (PMID 34008925, 2021). "The most sensitive cell lines were the DDLPS cell lines IB111, IB115 characterized by an amplification of the MDM2 gene and the extraskeletal osteosarcoma cell line IB128 with no alteration of the MDM2 gene copy numbers." (PMID 28903316, 2017). "The most sensitive cell lines were the DDLPS cell lines IB111 and IB115 characterized by an amplification of the MDM2 gene and the extraskeletal osteosarcoma cell line IB128 characterized with no alteration of the MDM2 gene copy numbers." (PMID 26427052, 2015). "However, new findings in immunohistochemistry with determination of MDM2 and CDK4 markers show promising results in distinguishing parosteal osteosarcoma from benign clinical and histological mimics." (PMID 24066980, 2013). "The ability of Nutlin-3a to induce apoptosis in tumours is variable, and osteosarcoma cell lines lacking MDM2 amplification are resistant to apoptosis." (PMID 21253554, 2011). "We found that silencing LPAATβ expression in osteosarcoma cells resulted in decreased expression of c-Myc, cyclin D1, c-Fos, and MDM2, but an increased Rb expression (data not shown)." (PMID 21152068, 2010).
osteosarcoma (continued). "For confirmation, the pathological samples removed in May 2004 were collected for re-examination, and notably for molecular analysis of MDM2 and CDK4 oncogenes, whose amplification had been reported in low-grade intraosseous and parosteal osteosarcomas." (PMID 21106072, 2010). "The presence of ABC-like features in osteosarcoma may obscure accurate diagnosis, but markers such as MDM2, CDK4, and the lack of USP6 rearrangement can provide critical diagnostic clues." (PMID 40926903, 2025). "Neither of the MDM2 inhibitors induced objective responses in osteosarcoma or neuroblastoma models, but in the limited number of models tested objective responses were noted for Ewing sarcoma (25 %), rhabdomyosarcoma (14 %), medulloblastoma (1 of 2), and other histologies." (PMID 39510293, 2024). "Group B included ten osteosarcomas, spanning low- and high-grade cases (three parosteal, two low-grade central, three dedifferentiated parosteal, and two conventional), all displaying amplification of CDK4 and MDM2, along with regions on chromosome arm 12p in all but three cases." (PMID 39322633, 2024). "MDM2 can also be deubiquitinated by USP2, and this may contribute to osteosarcoma tumorigenesis." (PMID 38534381, 2024). "Therefore, the MDM2 and CDK4, usually amplified in low‐grade osteosarcomas, might be key molecules involved in the tumorigenesis of low‐grade osteosarcomas." (PMID 34008925, 2021). "To determine whether USP48, through its ability to regulate NF-κB transcription factor, could play a role in the regulation of Mdm2 expression, we induced an siRNA-mediated knockdown of USP48 in human osteosarcoma U2OS cells and human lung carcinoma H1299 cells." (PMID 28233861, 2017). "Furthermore, genomic sequencing of 66 pediatric and adult osteosarcoma using MSK-Impact, a large Next Generation sequencing (NGS) assay has identified at least one targetable molecular alteration in 14 pts (21%) including amplification of CDK4 and/or MDM2 (14% each)." (PMID 34069999, 2021). "They found that all benign fibro-osseous lesions were negative for MDM2 and CDK4, while 89% of low-grade osteosarcomas were positive for both tests." (PMID 39105970, 2024). "The most sensitive cell lines were the DDLPS cell lines IB111 and IB115, characterized by MDM2 gene amplification, and the extraskeletal osteosarcoma cell line IB128, with no alteration in MDM2 copy number." (PMID 28629371, 2017).
lung carcinoma (167 papers, 1998 to 2025). "Under the double effect of the MDM2 rs2279744 polymorphism and cigarette smoking, the OR increased contrasted with that for smoking only, thus suggesting an enhanced risk of lung cancer (OR (95% CI) = 2.469 (1.116–5.461), P = 0.026)." (PMID 32513119, 2020). "A meta-analysis was conducted on the associations between theTP53 (rs1042522) and MDM2 (rs2279744) polymorphisms and lung cancer." (PMID 33959694, 2020). "Another 14 articles identified MDM2 (rs2279744) associationwith increased lung cancer risk were retrieved.These 14 articles encompassed case-controls studies involving lung cancer patients and 10,342 controls." (PMID 33959694, 2020). "Li G., Zhai X., Zhang Z., Chamberlain R.M., Spitz M.R. MDM2 genepromoter polymorphisms and risk of lung cancer: a case-controlanalysis." (PMID 33959694, 2020). "The combined OR indicated that the MDM2 rs2279744 polymorphism also correlated with an increasing risk of lung cancer in the overall population at a significant level (OR (95% CI) = 1.232 (1.054–1.410))." (PMID 32513119, 2020). "Zhang X., Miao M., Guo Y., Tan W., Zhou Y., Sun T., Wang Y., Lin D.Genetic polymorphisms in cell cycle regulatory genes MDM2 andTP53 are associated with susceptibility to lung cancer." (PMID 33959694, 2020). "The data on the associationof polymorphism of MDM2 (rs2279744 or 309T > G) withthe risk of developing lung cancer as well as in the case ofTP53 (rs1042522) are contradictory." (PMID 33959694, 2020). "Liu G., Wheatley-Price P., Zhou W. Genetic polymorphisms of MDM2,cumulative cigarette smoking and nonsmall cell lung cancer risk.Int." (PMID 33959694, 2020). "So far, seven studies have analyzed the association between c.309T>G of the MDM2 gene and lung cancer prognosis, but the results were contradictory." (PMID 27228500, 2016). "Among the three age-dependent markers, an increased relative expression of NF1 and WEE1 genes had a protective effect on subjects, whereas an increased relative expression of MDM2 gene was a risk factor for developing lung cancer." (PMID 27418131, 2016). "So far, seven studies have analyzed the association between c.309T>G of the MDM2 gene and lung cancer prognosis." (PMID 27228500, 2016). "Loss of DDX3 expression promoted tumor progression through MDM2/Slug/E-cadherin pathway in lung cancer." (PMID 26087195, 2015). "It has been reported that this polymorphism in the MDM2 gene is associated with the prognosis for several types of tumors, including lung cancer." (PMID 24040073, 2013). "By the Duplex SmartAmp method, we analyzed a total of 382 samples from Japanese patients with primary lung cancer for the presence of a genetic polymorphism in the MDM2 gene." (PMID 23565197, 2013). "Clinicopathological characterization of primary lung cancer patients as well as presence of SNP (c.309T>G) in the MDM2 gene and allele frequency." (PMID 23565197, 2013). "Updated meta-analyses examining the association between MDM2 T309G polymorphism and lung cancer risk were performed." (PMID 22844496, 2012). "In the subgroup analysis based on gender, we found that the MDM2 SNP309 GG genotype conferred a statistically significant increased risk of lung cancer development in females (OR, 1.282, 95%; CI, 1.062–1.548)." (PMID 23170107, 2012).
lung carcinoma (continued). "Murine double minute 2 (MDM2) SNP309 polymorphisms have been reported to influence the risk of lung cancer." (PMID 23170107, 2012). "Risk of lung cancer was higher among individuals with the MDM2 SNP309 TT genotype relative to the GG genotype (OR 2.10, 95% CI 1.01-4.36)." (PMID 20219101, 2010). "Taken together, the data indicate that the TT genotype of MDM2 SNP309 is associated with increased lung cancer risk." (PMID 20219101, 2010). "Reports have shown an increased risk of lung cancer for the G allele of the MDM2 SNP309 in Korean and Chinese populations." (PMID 18433484, 2008). "A combined analysis of the available genotype data of the MDM2 SNP309 showed an increased risk of lung cancer for the GG versus the TT genotype (OR: 1.3, 95% CI: 1.1–1.4)." (PMID 18433484, 2008). "However, if we want to verify the effect of smoking on lung cancer risk, the carrier status of the MDM2 rs2279744 polymorphism should be regarded as a stratified moderator and then controlled as well." (PMID 32513119, 2020). "Additionally, cigarette smoking had a nearly 1.70-times greater effect on increasing the risk of developing lung cancer (OR (95% CI) = 2.274 (1.015–5.094), P < 0.046), compared with the MDM2 rs2279744 polymorphism." (PMID 32513119, 2020). "In these two examples, an interesting result occurred when we studied the influence of NSAID intake on the cancer risk in the first meta-analysis and the effect of the MDM2 rs2279744 polymorphism or smoking on susceptibility to lung cancer in the second meta-analysis." (PMID 32513119, 2020). "Moreover, it has recently been reported that this polymorphism in the MDM2 gene is associated with the prognosis for several types of tumors, such as esophageal, pancreatic, and lung cancers." (PMID 23565197, 2013). "Consequently, ten publications containing eleven case-control studies regarding MDM2 T309G polymorphism with respect to lung carcinoma were included." (PMID 22844496, 2012). "However, the data failed to suggest a marked association between the G allele of MDM2 T309G and lung cancer risk among Asians." (PMID 22844496, 2012). "Given that estrogen receptors are expressed in lung tumours, particularly adenocarcinomas, and these cells are responsive to estrogen, it is possible that hormonal pathways provide an alternative mechanism by which MDM2 influences lung cancer risk in this population." (PMID 20219101, 2010). "Our findings reveal that the risk of lung cancer among individuals with the MDM2 SNP309 TT genotype was 2.1 (95% CI 1.01-4.36) relative to the GG genotype, contrary to initial expectations that the GG genotype with elevated MDM2 levels will increase cancer risk." (PMID 20219101, 2010). "Therefore one possible explanation would be, that the MDM2 variant is only associated with risk of later onset lung cancer." (PMID 18433484, 2008). "Contradictory results were reported regarding the MDM2 SNP309 association with lung cancer." (PMID 18433484, 2008). "The polymorphism SNP309 (rs2279744) in the promoter region of the MDM2 gene has been shown to alter protein expression and may play a role in the susceptibility to lung cancer." (PMID 18433484, 2008).